TLR4 (toll like receptor 4)
Diseases named in the same sentence as TLR4 in open-access papers (continued):
Sharing a sentence is not in itself a finding about the gene and the disease.
preeclampsia (33 papers, 2008 to 2025). Preeclampsia is a hypertensive disorder of pregnancy that is characterized by new-onset hypertension with proteinuria presenting after 20 weeks of gestation, and depending on mild or severe forms may initially present with severe headache, visual disturbances, and hyperreflexia. "It has also been demonstrated that antiphospholipid antibodies, which are implicated in the pathogenesis of recurrent miscarriages, preeclampsia, and premature labour, increase the inflammatory capacity of first-trimester trophoblasts via the TLR4 pathway." (PMID 39165943, 2024). "Pathway analysis of the gene expression data, using multiple predefined pathways, revealed decreased expression of TLR-associated genes in early-onset preeclampsia compared to healthy placentas (P=0.005), mainly due to reduced expression of TLR4 and TLR1." (PMID 34992598, 2021). "Single nucleotide polymorphisms in TLR2 (Arg753Gln) and TLR4 (Asp299Gly/Thr399Ile) have been associated with early onset of preeclampsia, with an exception in the Caucasian population." (PMID 32508811, 2020). "It has been observed that fetoplacental TLR4 expression is decreased in miscarriages and in preeclampsia patients, while the Tlr4 Asp299Gly polymorphism in the fetus is associated with severe prematurity." (PMID 31178840, 2019). "Preeclampsia is associated with over-activation of the innate immune system in the placenta, in which toll-like receptor 4 (TLR4) plays an essential part." (PMID 30008464, 2018). "VitD3 supplementation of pregnant women at risk of preeclampsia led to a decrease in TLR4 expression and a subsequent decrease in pro-inflammatory cytokine secretion ex vivo." (PMID 27506771, 2016). "Previous studies have also identified immune-system alterations associated with the origin of preeclampsia as well as genetic associations between TLRs and preeclampsia: TLR2 and TLR4 SNPs appear to alter susceptibility to developing preeclampsia." (PMID 26089598, 2015). "The toll-like receptor-4 (TLR-4) and factor V Leiden mutation participate both in development of preeclampsia and the HELLP syndrome." (PMID 24991435, 2014). "The screening of common TLR2 (2258 G>A) and co-segregating TLR4 (1063A>G and 1363C>T) SNPs in 94 women with preeclampsia and 176 healthy pregnancy controls showed the associations of these SNPs with early-onset but not late-onset preeclampsia." (PMID 23161283, 2013). "In summary, we are the first to show a relationship between allelic variants of TLR4, that impair the innate inflammatory response to LPS, early-onset preeclampsia and HELLP syndrome." (PMID 18382655, 2008). "Nonetheless, increasing tertiles of interleukin-6 and fibrinogen levels were associated with higher odds ratios for early-onset preeclampsia in women carrying one or more TLR4 or NOD2 mutations, compared to women with the wild-type TLR4 or NOD2 genotype." (PMID 18382655, 2008). "Among all women with a history of early-onset preeclampsia, positivity for one or more of the minor allelic variants of TLR4 was observed significantly more often than in controls, with an odds ratio of 3.3 (95% CI 1.5 to 7.5)." (PMID 18382655, 2008). "After adjustment for maternal age and chronic hypertension, attenuating allelic variants of TLR4 were more common in women with a history of early-onset preeclampsia than in controls (OR 2.9 [95% CI 1.2–6.7])." (PMID 18382655, 2008). "Furthermore, the activation of TLR4 promotes the senescence of placental mesenchymal stem cells, which is associated with damage in placental angiogenesis, and contributes to preeclampsia-like manifestations in rats." (PMID 40218311, 2025). "A role for reduced TLR4 signaling in early-onset preeclampsia was also suggested by a higher prevalence of allelic TLR4 gene variants with attenuated function in women with a history of early-onset preeclampsia." (PMID 34992598, 2021).
preeclampsia (continued). "Furthermore, CAV1 has been implicated in the mechanism of oedema in preeclampsia (PE) following hypoxia of trophoblasts through the HMGB1/TLR4/CAV-1 pathway." (PMID 32028606, 2020). "Among all TLRs, TLR4 has been found to be associated with preeclampsia." (PMID 32508811, 2020). "Previous studies suggested TLR-4 activation to be associated with inflammation in preeclampsia." (PMID 30079067, 2018). "As TLR4 mutations have been shown to determine susceptibility to a number of exogenous infectious agents, should we consider potential infectious agents responsible for causing preeclampsia or HELLP syndrome?" (PMID 18382655, 2008). "In an animal model of preeclampsia, the treatment with estrogen was also associated with beneficial responses, such as anti-inflammatory, antioxidant and anti-vascular dysfunction effects in placenta, which were partly mediated by suppression of TLR4 and its downstream signaling." (PMID 35822020, 2021). "In preeclampsia-like rat models, fisetin reduced the clinical and biochemical setting of PE by activation of Toll-like receptor 4 (TLR4)/NF-κB and NRF2/HO-1 pathways." (PMID 37296665, 2023). "Another interesting study reported that E2 reduced the level of CCL2 in the placenta to control inflammation and further treat preeclampsia (PE) via estrogen receptor Α36 (ERΑ36)-induced toll-like receptor 4 (TLR4) pathways." (PMID 36685497, 2022). "The results showed that early-onset preeclampsia placentas displayed reduced expression of complement, and toll-like receptor (TLR) associated genes, specifically TLR1 and TLR4." (PMID 34992598, 2021). "This suggests that the regulation of TLR4 is differently altered in preeclampsia in the fetal compared to the maternal compartment." (PMID 34992598, 2021). "Early-onset preeclampsia placentas displayed a decreased expression of TLR4, in agreement with earlier research, while studies in mild preeclampsia have reported either increased or unaltered TLR4 expression, similar to our late-onset preeclampsia patients." (PMID 34992598, 2021). "Trophoblastic glycometabolism reprogramming has now been noticed in the preeclampsia pathogenesis, plausibly modulated by the TLR4/NF-κB signaling as well." (PMID 34804360, 2021). "It is possible that this upregulation is part of a compensatory mechanism in preeclampsia, given that higher expression of TLR4 has been described in human term placentae compared to first trimester." (PMID 33013837, 2020). "An imbalance of the Th1 and Th2 response is a dominant immune response as a result of TLR4 activation which creates a pro-inflammatory environment leading to preeclampsia." (PMID 32508811, 2020). "Another factor, which is predisposed to preeclampsia, is the genetics of TLR2 and TLR4 polymorphism." (PMID 32508811, 2020). "Supporting this suggestion, a later study found a direct correlation between TLR-4 activation, inflammation, and plasma and placental oxidative damage in preeclampsia." (PMID 30079067, 2018). "In preeclampsia, the increased expression of TLR-4 by placental trophoblasts increases the secretion of trophoblast chemokines, thus attracting more monocytes to the decidua." (PMID 30079067, 2018). "Differences in the expression of TLR4 and its downstream target NF-κB p65 between the control and severe preeclampsia placenta were examined by immunostaining." (PMID 25853857, 2015). "TLR4 expression in severe preeclampsia placenta significantly increased in comparison to that in the control." (PMID 25853857, 2015). "TLR4 signaling in the placenta was activated, to which that in the placenta of humans with preeclampsia changed similarly." (PMID 25853857, 2015). "The aim of this study was to generate a rat model of preeclampsia by an administration of ultra-low-dose LPS around early placentation, and to assess the contribution of TLR4 signaling to the development of preeclampsia." (PMID 25853857, 2015).
preeclampsia (continued). "Combined positivity for any of the TLR-4 and NOD2 allelic variants and high levels of IL-6 were 6.9-fold more common in women with a history of early-onset preeclampsia than in healthy pregnant women (OR 6.9)." (PMID 24991435, 2014). "In the present study, we demonstrated that the allelic variants D299G and T399I of the extracellular pattern-recognition receptor TLR4, that impair the inflammatory response to LPS, are related to a history of early-onset preeclampsia." (PMID 18382655, 2008). "Combined positivity for any of the TLR4 and NOD2 allelic variants and high levels of interleukin-6 was 6.9-fold more common in women with a history of early-onset preeclampsia (95% CI 2.1–23.2) compared to controls." (PMID 18382655, 2008). "We observed an association of common TLR4 and NOD2 gene variants, and pro-inflammatory phenotype with a history of early-onset preeclampsia and HELLP syndrome." (PMID 18382655, 2008). "Of interest, preeclampsia appears more commonly in women who are seropositive for Chlamydia Pneumoniae, which is a TLR4 dependent intracellular pathogen related to the development of atheromatous lesions." (PMID 18382655, 2008). "In this study we examined the contribution of two common allelic variants of the TLR4 (D299G and T399I) and three common allelic variants of NOD2 (R702W, G908R and L1007fs) to the pathogenesis of early-onset preeclampsia and HELLP syndrome." (PMID 18382655, 2008). "The influence of TLR4 is particularly significant in the context of preeclampsia." (PMID 39596234, 2024). "Besides, from previous studies, it was found that gastrodin can suppress the apoptosis induced by preeclampsia by regulating the TLR4/NF-κB of HTR/SVneo cells." (PMID 34424813, 2021). "In contrast to a decreased placental TLR4 expression as identified in the present study, previous studies have shown that the expression of TLR4 was elevated in the circulating innate immune cells of women with preeclampsia." (PMID 34992598, 2021). "ATF3 has been shown to cross-talk to NF-κB and to act as a negative regulator of pro-inflammatory responses in different settings, such as preeclampsia, inflammation after cerebral injury, and Toll-like receptor 4 signaling, in the latter case by direct binding to the p65/RelA subunit of NF-κB." (PMID 35115943, 2021). "Herewith, we investigated whether pravastatin could ameliorate preeclampsia-like phenotypes in a previously established lipopolysaccharide (LPS)-induced rat preeclampsia model, through targeting the TLR4/NF-κB pathway." (PMID 30008464, 2018). "The expression of TLR4 was demonstrated increased in the placenta of women with preeclampsia." (PMID 25853857, 2015). "Accumulating evidence shows that pathological stimuli may predispose immune maladaptation and abnormal placentation observed in preeclampsia, in which the toll-like receptor 4 (TLR4) is playing a vital role." (PMID 25853857, 2015). "As the downstream of LPS signaling, TLR4/NF-κB signal pathway might involve multiple symptoms of preeclampsia." (PMID 25853857, 2015). "Among of them, TLR4 is a major contributor to the development of human preeclampsia." (PMID 25853857, 2015). "This study showed that preeclampsia sera stimulate expression of TLR4 and TLR9 in adipose tissue." (PMID 26089598, 2015). "The expression of TLR4 and its downstream target NF-κB p65 were both increased in the placenta from LPS-treated pregnant rats, which mimicked the changes observed in human placenta from patients with preeclampsia." (PMID 25853857, 2015). "TLR4 generates local and systemic inflammatory and oxidative stress responses in preeclampsia." (PMID 26089598, 2015). "RT-qPCR confirmed aberrant expression of genes involved in inflammation and stress response (TLR4 and TLR9) and also genes involved in host defense (PRDX5, MIF, CD74, NFE2L1, and CSF3R), suggesting that preeclampsia sera suppress the TLR4/9-dependent excess oxidative stress in adipose tissue." (PMID 26089598, 2015).
preeclampsia (continued). "Interestingly, increased TLR4 expression was found in the placenta from the patients with preeclampsia." (PMID 25853857, 2015). "In women with preeclampsia a persistent TLR-4 signal could reverse the CD4+CD25bright Treg cell-mediated immunosuppression." (PMID 24991435, 2014). "We hypothesized that allelic variants of TLR4 and NOD2, as well as high circulating levels of pro-inflammatory biomarkers after delivery would relate to a history of early-onset preeclampsia and HELLP syndrome." (PMID 18382655, 2008). "We determined five common mutations in TLR4 (D299G and T399I) and NOD2 (R702W, G908R and L1007fs) in 340 primiparous women with a history of early-onset preeclampsia, of whom 177 women developed HELLP syndrome and in 113 women with a history of only uneventful pregnancies as controls." (PMID 18382655, 2008). "We examined whether allelic variants of the innate immune receptors Toll-like receptor 4 (TLR4) and nucleotide-binding oligomerization domain 2 (NOD2), that impair the inflammatory response to endotoxin, are related to preeclampsia and HELLP syndrome." (PMID 18382655, 2008). "First, that maternal predisposition to early-onset preeclampsia and HELLP syndrome is associated with allelic variants of genes that impair the innate immune response, as demonstrated by the association with common TLR4 polymorphisms." (PMID 18382655, 2008). "Interestingly, recent data by Kim and colleagues showed increased expression of TLR4 in interstitial trophoblasts in placental bed biopsies obtained from women with preterm preeclampsia, consistent with a role for TLR4 at the feto-maternal interface." (PMID 18382655, 2008). "In our study, TLR4 mutations were 2.4 times more common in women with HELLP syndrome than those with preeclampsia only, suggesting that the TLR4 pathway might be involved in the development of HELLP episodes in women with early-onset preeclampsia." (PMID 18382655, 2008). "Therefore, supplementation of Tollip or treatment with different TLR4 inhibitors could be an efficient therapeutic option for preeclampsia." (PMID 33445783, 2021). "Therefore, through the activation of TLR-4, bacterial stimuli may contribute to the oxidative, inflammatory, and metabolic stresses in preeclampsia." (PMID 30079067, 2018). "In addition, TLR4 polymorphisms were significantly more common in women who developed HELLP syndrome, when compared to women with preeclampsia only (excluding those with HELLP) with an OR of 2.3 (95% CI 1.3 to 4.3) after adjustment for maternal age and chronic hypertension." (PMID 18382655, 2008). "To confirm the presence of vital NETosis in normal pregnancy and in pregnancy complicated by preeclampsia, we performed experiments using anti-TLR2 and anti-TLR4 blocking antibodies." (PMID 36684420, 2022). "The TLR4 expression in trophoblast cells was notably elevated in women who had preterm birth due to preeclampsia compared to those who had preterm delivery with or without complementary and alternative medicine (CAM) therapies." (PMID 39165943, 2024). "A recent study has found that inhibition of the trophoblast TLR4/NF-κB/PFKFB3 signaling pathway to correct glycometabolic reprogramming and NLRP3 inflammation-induced pyroptosis may be a treatment approach for preeclampsia." (PMID 36589684, 2022). "TLR4 activation by bacterial LPS, in addition, inhibits trophoblast migration, while TLR3 activation by poly I:C, a double-stranded RNA (dsRNA) viral mimetic, increases inflammation and results in the development of preeclampsia-like symptoms in pregnant rats." (PMID 33013837, 2020). "The TLR4 and TLR9 activation in adipose tissue may worsen the situation of patients with preeclampsia." (PMID 26089598, 2015). "This means that the TLR-4 pathway and the innate immune system might be involved in development of both the HELLP syndrome and early-onset preeclampsia." (PMID 24991435, 2014).
preeclampsia (continued). "Our study verified that the TLR4/NF-κB/PFKFB3 signaling might be a novel link between the reprogrammed glycometabolism and trophoblastic pyroptosis, providing novel insights into the pathogenesis of preeclampsia." (PMID 34804360, 2021). "Furthermore, in research on the pathophysiology of pre-eclampsia (PE), hypoxic trophoblasts displayed higher intracellular HMGB1 protein levels which could increase TLR4 and Caveolin-1." (PMID 31284269, 2019).